MTA1 (metastasis associated 1)
Diseases named in the same sentence as MTA1 in open-access papers (continued):
Sharing a sentence is not in itself a finding about the gene and the disease.
prostate carcinoma (continued). "Based on these findings, DNA or RNA alterations of YB-1 and MTA1 cannot distinguish between normal prostate and prostate cancer tissues." (PMID 25797255, 2015). "YB-1 and MTA1 are the first translationally regulated biomarkers to be identified that significantly correlate with disease behavior in prostate cancer." (PMID 25797255, 2015). "Analysis of the fold change of YB-1 and MTA1 transcript levels in normal prostate tissue compared to prostate cancer tissues using the curated Oncomine database (n = 1016 normal and prostate cancer specimens)." (PMID 25797255, 2015). "It has been reported that MTA1 regulates E-cadherin expression via AKT activation in prostate cancer, and that miR-21 is required for regulation of phosphorylated AKT expression in glioblastoma multiforme." (PMID 25609245, 2015). "Silencing of MTA1 also impairs the angiogenesis of prostate cancer, partially eliminating the circumstance of cancer growth." (PMID 24396455, 2014). "MTA1 has also been reported to regulate the anoikis of human prostate cancer cells, which reveals a new subfield of MTA1 mechanisms." (PMID 24396455, 2014). "This study also provides a new mechanistic role for MTA1 in the regulation of prostate cancer metastasis." (PMID 23227138, 2012). "The protein and mRNA levels of MTA1 were significantly higher in the highly metastatic prostate cancer PC-3M-1E8 cells than in the poorly metastatic prostate carcinoma PC-3M-2B4 cells." (PMID 23227138, 2012). "In this study, we demonstrate that MTA1 changes the malignant phenotype of prostate cancer cells and regulates the expression of E-cadherin by an AKT phosphorylation-dependent mechanism." (PMID 23227138, 2012). "In prostate cancer, a DNA microarray demonstrated that MTA1 is selectively over-expressed in metastatic prostate cancer compared to clinically localized prostate cancer or benign prostate tissue." (PMID 23227138, 2012). "We show that MTA1 is expressed in over 90% of prostate cancer tissues, especially metastatic prostate cancer tissue, comparing to non-expression in normal prostate tissue." (PMID 23227138, 2012). "RT-PCR analysis and Western blot assay showed that MTA1 expression is significantly higher in highly metastatic prostate cancer PC-3M-1E8 cells (1E8) than in poorly metastatic prostate cancer PC-3M-2B4 cells (2B4)." (PMID 23227138, 2012). "All of these results demonstrate that MTA1 plays an important role in controlling the malignant transformation of prostate cancer cells through the p-AKT/E-cadherin pathway." (PMID 23227138, 2012). "A better understanding of the mechanisms of metastasis genes like MTA1 provides greater insight into the metastasis of prostate carcinoma as well as a potential therapeutic target for the treatment of metastasis." (PMID 23227138, 2012). "To elucidate the mechanism of MTA1 in prostate cancer metastasis, we chose the metastatic prostate cancer PC-3M-1E8 cell line that contained a high level of MTA1 for subsequent analysis." (PMID 23227138, 2012). "An immunohistochemistry analysis demonstrated that MTA1 was over-expressed in prostate cancer tissues, especially in metastatic prostate cancer tissue." (PMID 23227138, 2012). "In the current study, MTA1 has been shown for the first time, to elicit a humoral immune response in prostate cancer patients." (PMID 18949081, 2008). "MTA1 mRNA is highly expressed in human prostate cancer cell lines and a significant number of prostate, renal and stomach cancer tissues." (PMID 18949081, 2008). "We, too, have shown an inverse correlation between MTA1 and E-cad in human prostate cancer." (PMID 40351767, 2025). "However, comprehensive mechanistic and preclinical studies in prostate cancer support AR- and MTA1-targeted chemopreventive, interceptive and therapeutic effects of Gnetin C." (PMID 40077738, 2025).
prostate carcinoma (continued). "Collectively, these findings established gnetin C as a new natural compound with anticancer properties against MTA1/AKT/mTOR-activated prostate cancer, with potential as monotherapy and as a possible adjunct to clinically approved mTOR pathway inhibitors in the future." (PMID 38611022, 2024). "Therefore, in the future, combinatorial targeted therapies can be beneficial to a biomarker-selected subpopulation of patients with MTA1/mTOR activation-mediated advanced prostate cancer." (PMID 38611022, 2024). "Based on our previous findings, we hypothesized that gnetin C might be effective as an MTA1-targeted therapeutic agent against advanced prostate cancer." (PMID 38611022, 2024). "Similar to Resveratrol, Pterostilbene targets MTA1 in prostate cancer cells." (PMID 38155902, 2023). "Moreover, the MTA1/HDAC unit is one of the negative regulators of PTEN that encourages prostate cancer development and survival pathways that is suppressed by resveratrol’s MTA1 inhibitory action." (PMID 35566016, 2022). "The clinical significance of MTA1 in prostate cancer progression and metastasis has been reported." (PMID 36551523, 2022). "To evaluate gnetin C’s clinical potential, in the current study, we assessed the efficacy of gnetin C-supplemented diets as MTA1-targeted interception using a unique transgenic mouse model (R26MTA1; Pten+/f; Pb-Cre+) representing high-risk early-stage prostate cancer." (PMID 36551523, 2022). "Our special interest in oncomiR/PTEN axis came from previous studies, in which we and others showed upregulation of PTEN protein levels by resveratrol in prostate cancer cells, one mechanism of which was the inhibition of MTA1-mediated deacetylation and inactivation of PTEN." (PMID 36091792, 2022). "Besides, it has been evidenced that MTA1 participates in the regulation of HIF-α, by which MTA1 promotes tumor invasion and progression in pancreatic cancer and prostate cancer." (PMID 33282725, 2020). "Given that we have previously shown that IL-17 promotes development of prostate cancer, we reason that IL-17 may at least partially act through upregulating MTA1 to promote prostate cancer formation based on the findings from the present study." (PMID 31281798, 2019). "High levels of MTA1 were detected in bone metastatic lesions of human prostate cancer patients." (PMID 30027683, 2018). "Altogether, MTA1 is increasingly being recognized as an important upstream multifunctional regulator that affects various cellular responses, including cell adhesion, migration, and invasion in prostate cancer." (PMID 30027683, 2018). "In addition, copy number analysis data of the prostate cancer patient samples from independent studies showed an amplification of MTA1 and CTSB." (PMID 30027683, 2018). "Thus, MTA1 is an attractive target for the treatment of prostate cancer and prevention of bone metastasis." (PMID 30027683, 2018). "In prostate cancer, a phosphatase and tensin homolog (PTEN), a tumor suppressor, is deleted on chromosome 10 or inactivated by the negative regulator metastasis-associated protein 1 (MTA1)/HDACs." (PMID 29104258, 2017). "We believe that our present findings of chemopreventive and therapeutic efficacy of an epigenetic dietary agent pterostilbene as a novel MTA1-targeted strategy, may have potential clinical applications in prostate cancer management." (PMID 26943043, 2016). "Our data appear highly clinically relevant because they support the concept that patients with deregulated PTEN/Akt pathway, which comprise 21–42% of prostate cancer patients, most likely have overexpression of MTA1 and may benefit from MTA1-targeted therapy." (PMID 26943043, 2016).
prostate carcinoma (continued). "Our serendipitous finding of MTA1 as a new molecular target of resveratrol and its analogs opened opportunities for further pre-clinical validation of the efficacy of pterostilbene as natural epigenetic therapy in prostate cancer." (PMID 26943043, 2016). "Moreover, the expression of E-cadherin (an epithelial marker) was downregulated along with upregulation of Vimentin (a mesenchymal marker), indicating the involvement of MTA1 in epithelial-to-mesenchymal transition (EMT) of prostate cancer cells." (PMID 26943043, 2016). "We found that loss of only one Pten allele was sufficient to substantially increase MTA1 both at protein and mRNA levels, suggesting that MTA1 may be involved in the initiation stage of prostate cancer." (PMID 26943043, 2016). "Thus, a combinatorial approach, which includes clinical factors and translationally regulated biomarkers such as YB-1 and MTA1, represents a potentially powerful method to predict for future prostate cancer behavior after a prostatectomy." (PMID 25797255, 2015). "However, very little is known about how YB-1 and MTA1 are together deregulated in human prostate cancer tissues." (PMID 25797255, 2015). "Importantly, YB-1 and MTA1 protein levels significantly increase the predictive capacity of a clinical model for prostate cancer recurrence." (PMID 25797255, 2015). "Importantly, YB-1 and MTA1 have been shown to endow immortalized epithelial cells with invasive properties and are necessary to maintain the invasive potential of prostate cancer cells." (PMID 25797255, 2015). "Little is known regarding how MTA1 functions to regulate metastasis in prostate cancer." (PMID 23227138, 2012). "However, in the localized prostate cancer samples, positive staining for MTA1 was observed in the nuclei of 6 of the 15 tissues examined." (PMID 23227138, 2012). "Additionally, in 27 of the 30 tumor metastatic prostate cancer tissues, a high level of MTA1 staining was observed in both the cytoplasm and nuclei of the cancerous cells." (PMID 23227138, 2012). "Therefore, the 1E8 cell line was chosen to investigate the biological properties of MTA1 in prostate carcinoma in vitro." (PMID 23227138, 2012). "Our results also indicate that the MTA1 gene may play an important role in the invasion and metastasis of prostate cancer." (PMID 23227138, 2012). "The pathway most affected by MTA1 overexpression in the PTEN-loss prostate was the mTORC1 (hereafter mTOR) pathway, which is known to be aberrantly activated in castration-resistant prostate cancer and advanced prostate cancer with a reduced expression of PTEN." (PMID 38611022, 2024). "Besides, overexpression of MTA1 in prostate cancer results in tumor invasion and metastasis." (PMID 38155902, 2023). "Therefore, the current study was undertaken to examine the promising MTA1/PTEN/Akt-mediated chemopreventive and interceptive properties of gnetin C, a dimeric stilbenoid, using a clinically relevant model of murine prostate cancer representing high-risk premalignant neoplasia." (PMID 36551523, 2022). "This emphasizes that MTA1-targeted interception by diet supplemented with gnetin C may have greater potential benefits compared to pterostilbene supplementation, which we have recently reported for prostate cancer chemoprevention." (PMID 36551523, 2022). "Importantly, in a recent paper using genetically modified DU145 and PC3M prostate cancer cells, gnetin C was shown to have more potent MTA1-mediated cytotoxicity, apoptosis, inhibition of clonogenic cell survival, and motility compared to resveratrol and pterostilbene." (PMID 36551523, 2022). "The development of natural and synthetic MTA1 inhibitors with improved pharmacokinetic profiles will secure the utilization of these new and targeted drugs not only for interception during early-stage prostate cancer, but also in the treatment of more advanced stages and metastatic disease." (PMID 36551523, 2022).
prostate carcinoma (continued). "Additionally, MTA1 inhibition by pterostilbene, a compound that has a similar structure and function to resveratrol, in combination with a HDACi has shown to be effective in a prostate cancer mouse model." (PMID 34968229, 2019). "Together, these results demonstrate the critical role of MTA1 as an upstream regulator of CTSB‐mediated events associated with cell invasiveness and raise the possibility that targeting MTA1/CTSB signaling in the tumor may prevent the development of bone metastasis in prostate cancer." (PMID 30027683, 2018). "In our previous studies, we have identified metastasis‐associated protein 1 (MTA1) as a novel factor involved in ‘vicious cycle’ of prostate cancer cells interacting with bone cells, and hypothesized that MTA1 may play a specific role in prostate cancer bone metastasis." (PMID 30027683, 2018). "However, it is not known whether the resulting protein levels of translationally controlled mRNAs such as YB-1 and MTA1 can together predict prostate cancer patient outcomes." (PMID 25797255, 2015). "Thus, translationally regulated mRNAs such as YB-1 and MTA1 may serve as biomarkers whose expression trend with the natural history of prostate cancer development and progression." (PMID 25797255, 2015). "Together these data suggest that the MTA1 signaling plays an essential role in the development and progression of metastatic prostate cancer and that targeting MTA1 pathway by dietary polyphenols may be effective in slowing down tumor progression and preventing metastasis." (PMID 23469203, 2013). "Similarly, in an advanced prostate cancer model, Gnetin C (7 mg/kg/bw, i.p.)significantly blocked tumor progression through MTA1/Akt/mTOR signaling, suggesting that Gnetin C could be effective not only in cancer chemoprevention and interception but also as an active therapeutic strategy." (PMID 40077738, 2025). "Therefore, our R26MTA1; Ptenf/f mice mimic a subtype of advanced prostate cancer that exhibits the involvement of mTOR signaling, suggesting that targeting the MTA1/mTOR pathway by natural stilbene gnetin C could be an effective means for blocking prostate cancer progression." (PMID 38611022, 2024). "When combined with SAHA, a clinically approved HDAC inhibitor, Pterostilbene enhanced sensitivity to SAHA treatment by targeting MTA1 and HDAC via the same pathway in prostate cancer." (PMID 38155902, 2023). "Collectively, these data demonstrate a more potent MTA1/PTEN/Akt response to gnetin C than to pterostilbene treatment, both in a murine prostate model of early-stage prostate cancer and in a prostate cancer cell line." (PMID 36551523, 2022). "Resveratrol downregulated the MTA1/HDAC unit of the NuRD complex and then promoted PTEN acetylation, thus blocking the PTEN/Akt pathway and inhibiting the progression of prostate cancer." (PMID 34924813, 2021). "Resveratrol downregulated the MTA1/HDAC complex and facilitated PTEN acetylation, thus blocking the PTEN/Akt pathway and inhibiting the progression of prostate cancer." (PMID 34924813, 2021). "In prostate cancer, RVT has been demonstrated to lead to the promotion of acetylation on Lys125 and Lys128 of PTEN as well as its reactivation by inhibiting of the MTA1/HDAC complex, which results in the inactivation of the PKB pathway." (PMID 30884859, 2019). "A recent study found that MTA1 silencing in human prostate cancer PC3M cells diminished formation of bone metastases and impaired tumor growth in intracardiac and subcutaneous prostate cancer xenografts, respectively." (PMID 31281798, 2019). "This suggests that the MTA1/HDAC complex regulates negatively the PTEN, and thus promotes proliferation as well as metastasis of prostate cancer, and that RVT can abrogate these key oncogenic hallmarks through the inhibition of MTA1." (PMID 30884859, 2019).
prostate carcinoma (continued). "It has been reported that in prostate cancer cells, there is an inverse correlation between MTA1 and PTEN, as MTA1 is a negative regulator of PTEN via modulating the deacetylation and inactivation of PTEN47." (PMID 30814496, 2019). "Of note, MTA1 and CTSB exhibited a strong positive correlation from 69 prostate cancer patient samples (r = 0.38)." (PMID 30027683, 2018). "We have previously reported on MTA1 knockdown inhibiting the tumor growth and progression of the LNCaP and DU145 s.c. prostate cancer xenografts." (PMID 30027683, 2018). "The downregulation of MTA1 by RVT disrupts the MTA1/HDAC complex, activating the proapoptotic genes Bax and p21 and triggering apoptosis in prostate cancer cell lines (PCa)." (PMID 29104258, 2017). "MTA1 reportedly regulates E-cadherin expression by activating AKT, promoting prostate cancer cell invasion and metastasis." (PMID 28418915, 2017). "We found a reduction in NF-κB (p65), IL-1β, and Vimentin and upregulation of E-cadherin protein levels in MTA1 knockdown (shMTA1) prostate cancer cells, suggesting direct involvement of MTA1 in inflammation and EMT in prostate cancer." (PMID 26943043, 2016). "We next determined the independent predictive value of YB-1 and MTA1 levels on the clinically important outcome of PSA recurrence, which is typically the first indicator of disease relapse in prostate cancer patients after surgery." (PMID 25797255, 2015). "Instead, our findings indicate a striking correlation between high protein levels of YB-1 and MTA1 with PSA recurrence, which is the first indicator of prostate cancer progression after definitive localized therapy." (PMID 25797255, 2015). "Taken together, these findings suggest the existence of a new MTA1-dependent pathway, the MTA1/p-AKT/E-cadherin pathway, which controls the malignant phenotype in prostate cancer cells." (PMID 23227138, 2012). "In this study, we demonstrate that the silencing of MTA1 by siRNA treatment results in the upregulation of E-cadherin expression by the phosphorylation of AKT (p-AKT) and decreases the invasiveness of prostate cancer cells." (PMID 23227138, 2012). "In this study, we employed a prostate-specific transgenic mouse model with MTA1 overexpression on the background of phosphatase and tensin homolog (Pten) null (R26MTA1; Ptenf/f) and PC3M prostate cancer cells which recapitulate altered molecular pathways in advanced prostate cancer." (PMID 38611022, 2024). "To gain initial insights regarding the mechanistic basis for targeting the MTA1/mTOR pathway, we first investigated the link between MTA1 and mTOR signaling in PC3M prostate cancer cells, which are known to have a PTEN-null status and the highest MTA1 expression of all prostate cancer cell lines." (PMID 38611022, 2024). "Among the downstream pathways affected by the changes in MTA1 levels is the phosphatase and tensin homolog/v-akt murine thymoma viral oncogene (protein kinase B) (PTEN/Akt) pathway, the deregulation of which plays an essential role in prostate cancer." (PMID 36551523, 2022). "The authors further demonstrated a reverse correlation between PKD1 and MTA1 expression in a transgenic adenocarcinoma of the mouse prostate (TRAMP) model and in samples of human prostate cancer, in which PKD1 expression decreased, whereas MTA1 expression increased with progressed tumor stage." (PMID 33807058, 2021). "Thus, MTA1/HDAC complex is a negative regulator of PTEN, which promotes tumor cell survival and progression of prostate cancer." (PMID 30881375, 2019). "In fact, MTA1 was identified by a SEREX approach, and researchers detected a natural MTA1-specific humoral immune response in prostate cancer patients but not healthy donors, indicating that MTA1 is immunogenic in patients." (PMID 30596107, 2018).